CD40LG (CD40 ligand)
Diseases named in the same sentence as CD40LG in open-access papers (continued):
Sharing a sentence is not in itself a finding about the gene and the disease.
atherosclerosis (284 papers, 1998 to 2026). A disease characterized by the build-up of fatty material and calcium deposition in the arterial wall resulting in partial or complete occlusion of the arterial lumen. "(2011) investigated the relationship between prolactin levels and atherosclerosis risk factors of soluble CD40 ligand (sCD40L) and high‐sensitivity C‐reactive protein (hs‐CRP) in migraineurs between attacks." (PMID 37190874, 2023). "Inflammation regulates atherogenesis and soluble CD40 ligand (sCD40L) is an inflammatory mediator associated with the presence of single-territorial atherosclerosis." (PMID 33406736, 2021). "Platelets chemokines (e.g. RANTES, PF4, SDF-1, MCP-1, CXCL5, CXCL7) and newly synthesized active cytokine-like factors [e.g. IL-1β, CD40 ligand (CD40L), β-thromboglobulin] are implicated in the development of atherosclerosis." (PMID 23372649, 2013). "In the present study, we aimed to investigate the relationship between prolactin levels and subclinical atherosclerosis risk factors such as soluble CD40 ligand (sCD40L) and high-sensitivity CRP (hsCRP) in migraine patients during interictal period." (PMID 21331754, 2011). "A previous study presented an immunomagnetic assay based on functionalized magnetic beads and detachable QDs for the separation and quantication of soluble CD40 Ligand (CD40 Ligand, also known as tumor necrosis factor associated activation protein, is related to atherosclerosis) from solution." (PMID 32923434, 2020). "The interaction between CD40 and CD40 ligand (CD40L), a crucial co-stimulatory signal for activating adaptive immune cells, plays a critical role in atherosclerosis." (PMID 40429638, 2025). "FTO plays a crucial role in regulating atherosclerosis by directly mediating the expression of CD40 ligand (CD40L)." (PMID 39787159, 2025). "Soluble CD40 ligand (sCD40L): sCD40L, a member of the TNF-α family, is linked to platelet activation, atherosclerosis, and endothelial dysfunction." (PMID 40001586, 2025). "Expression of CD40LG on various vascular cells contributes to the pathogenesis of atherosclerosis, thrombosis, and inflammatory processes." (PMID 37744382, 2023). "Soluble CD40 Ligand (sCD40L) is a mediator of vascular inflammation that is implicated in atherogenesis, activating CD40 receptor on various cells that contribute to atherosclerosis progression (e.g., on macrophages, endothelial cells and T-cells)." (PMID 35628490, 2022). "The CD40/CD40 ligand (CD40L) dyad plays a significant role in several immunogenic and inflammatory processes, including atherosclerosis." (PMID 35955688, 2022). "Previous studies showed that inhibition of the co-stimulatory CD40 ligand (CD40L)-CD40 signaling axis profoundly attenuates atherosclerosis." (PMID 34145241, 2021). "The atherosclerosis plaque destabilization network accurately described the important role of CD40LG in the regulation of chemotaxis, the immune and inflammatory responses, and extracellular matrix disassembly." (PMID 26200752, 2015). "The CD40LG node had the largest degree of distribution, suggesting a central role for this ligand in the atherosclerosis plaque destabilization network." (PMID 26200752, 2015). "CD40 and CD40 ligand (CD40L) have a critical role in the pathophysiology of atherosclerosis and atherothrombosis." (PMID 26289439, 2015). "It was reported that CD40-CD40 ligand (CD40L) signaling, a T cell co-stimulatory receptor-ligand pair, plays a crucial role in atherosclerosis." (PMID 24398220, 2014). "Further experiments using Cd40lg−/−Apoe−/− mice have demonstrated a proatherogenic role for CD40L in advanced atherosclerosis by promoting lipid core formation and plaque destabilisation." (PMID 22577254, 2012). "As it is highly expressed in atheromatous plaques also, inhibitors of CD40/CD40 ligand pathway can be novel molecules for delaying progression of atherosclerosis." (PMID 21572750, 2010).
atherosclerosis (continued). "Research concerning the CD40 ligand demonstrated its commitment to the development of the inflammatory process in various diseases, including cardiovascular diseases and atherosclerosis, as well as inflammatory bowel diseases such as colitis ulcerosa or Crohn’s disease." (PMID 34441316, 2021). "Recent data also suggest new potential risk factors for atherosclerosis and platelet aggregation such as brain-derived neurotrophic factor (BDNF), sCD40L (soluble CD40 ligand), serpin E1/PAI I (endothelial plasminogen activator inhibitor), and vascular endothelial growth factor (VEGF)." (PMID 33020432, 2020). "CD40 and CD40 ligand activation are known to be important inflammatory signals in atherosclerosis." (PMID 26095681, 2015). "Additional biomarkers implicated in AS-related atherosclerosis include elevated asymmetric dimethylarginine (ADMA), an endogenous NOS inhibitor, and persistent platelet activation post-anti-TNF therapy, evidenced by increased platelet-monocyte complexes (PMC) and soluble CD40 ligand (sCD40L) levels." (PMID 40229608, 2025). "The interaction between CD40 and CD40 ligand (CD40L) a crucial co-stimulatory signal for activating adaptive immune cells, has a noteworthy role in atherosclerosis." (PMID 38579073, 2024). "Activated platelets secrete secondary mediators such as ADP, CD40 ligand (CD40L), cytokines, and matrix metalloproteinases (MMPs), which, besides enhancing platelet activation, can modulate inflammation and atherosclerosis." (PMID 36422558, 2022). "Inflammation is an important determinant of progression of atherosclerosis and post-thrombotic syndrome which complicates deep vein thrombosis (DVT) through CD40/CD40 ligand pathway and P selectin." (PMID 21572750, 2010). "A cluster of differentiation 40 (CD40) and CD40 ligand (CD40L, costimulatory molecules that belong to the superfamily of tumor necrosis factor (TNF) proinflammatory chemokines are contributory to the burden of atherosclerosis, plaque stability, and prothrombotic effects." (PMID 40573228, 2025). "However, data emerging from experimental models of atherosclerosis indicate that IFN-γ, TNF-α, and CD40 ligand (CD154) produced by Th-1 CD4+ T-cell responsive to antigens in oxidized LDL drive plaque macrophages to produce reactive oxygen species, NO, and proinflammatory cyto/chemokines." (PMID 22229098, 2012).
autoimmune disease (284 papers, 2003 to 2026). A disorder resulting from loss of function or tissue destruction of an organ or multiple organs, arising from humoral or cellular immune responses of the individual to their own tissue constituents. "However, increased expression of CD40 ligand (CD154) leading to more CD40 activation is associated with autoimmune diseases including SLE and Sjögren’s disease, both of which also affect patients with TRAF3 haploinsufficiency (12, 36, –38)." (PMID 40773231, 2025). "Soluble CD40 ligand (sCD40L) is elevated in various autoimmune disorders, which may have diagnostic and therapeutic implications." (PMID 31782290, 2020). "In addition, mutations of CD40LG were observed in patients with the hyper-immunoglobulin M (IgM) syndrome, and genetic variations located at the 3UTR of the CD40LG gene were associated with two autoimmune diseases, SLE and RA." (PMID 22731751, 2012). "The interaction between mCD40 and CD40 ligand (CD40L) plays an important role in several autoimmune diseases, including rheumatoid arthritis, autoimmune nephritis, and PBC." (PMID 36825008, 2023). "Soluble CD40 ligand (sCD40L) and soluble interleukin-2 receptor (sCD25) are abnormally expressed in autoimmune diseases and are reliable markers of inflammation." (PMID 35996408, 2022). "CD40-CD40 ligand (CD40-CD40L) is a key receptor–ligand signaling pair involved in the adaptive immune response and pathogenesis of autoimmune diseases." (PMID 34440067, 2021). "Biologics have been developed to block activity of the CD40 ligand (CD40L) in order to reduce reactivity in autoimmune diseases, however antibody biologics mimic the actual autoimmune antibodies generated as part of the disease." (PMID 32143310, 2020). "Given its central role as a key regulator and amplifier of immune reactivity, the CD40/CD40 ligand (CD40L) system significantly contributes to the development and progression of multiple autoimmune diseases, including IBD." (PMID 26528290, 2015). "It has been observed that CD154 (CD40 ligand) plays a key role in the production of pro-inflammatory cytokines and it has been linked to various autoimmune diseases with microvascular complications, like diabetes mellitus." (PMID 25723058, 2014). "The important role of the CD40-CD40LG pathway in autoimmunity, together with the association of the CD40 gene with a number of autoimmune diseases, prompted us to investigate for the first time the contribution of CD40 and CD40LG genes in SSc." (PMID 22731751, 2012). "The CD40/CD40-ligand pathway is a key component of the pathophysiology of numerous autoimmune disorders." (PMID 20634952, 2010). "The role of the CD40LG in the susceptibility to autoimmune diseases has not been investigated as broadly as that of CD40, mainly because this gene is located on the × chromosome." (PMID 22731751, 2012). "Interesting findings arise from the observation that CD40–CD40 ligand (CD40L/CD154) interaction, a crucial step in autoimmune disease pathogenesis, is thought to be involved in atherogenesis and plaque rupture in RA." (PMID 23166616, 2012). "Previous papers links CD40LG to the Hyper-IgM syndrome with secondarily increased prevalence of autoimmune diseases as sero-negative arthritis, hypothyroidism, hepatitis, and inflammatory bowel disease." (PMID 27687697, 2016).
Autoimmunity (200 papers, 2004 to 2026). The occurrence of an immune reaction against the organism's own cells or tissues. "X-linked hyper-IgM syndrome (XHIM) is caused by mutations in the CD40 ligand (CD40L) gene that result in ineffective antibody production, recurrent infections, and autoimmunity in male infants." (PMID 38786024, 2024). "CD40LG, also known as CD40L, is a type II transmembrane protein that is crucial for regulating autoimmunity and cell death." (PMID 38774864, 2024). "The CD40-CD40 ligand pathway plays a significant role in both autoimmunity and adaptive immunity, Studies have suggested that this pathway also contributes to the pathophysiology of diabetes mellitus." (PMID 37959396, 2023). "KGD is also known to be present within the CD40 ligand (CD40L) which together with CD40 forms an important dyad relevant for mounting an immune response, autoimmunity, and inflammation; for example, its role has recently been suggested in immunopathology of certain forms of glomerulonephritis." (PMID 29666617, 2018). "Dazodalibep (DAZ), a novel nonantibody fusion protein, is a CD40 ligand antagonist that blocks costimulatory signals between T and B cells and antigen-presenting cells, and therefore may suppress the wide spectrum of cellular and humoral responses that drive autoimmunity in SjD." (PMID 38839899, 2024).
Immunodeficiency (176 papers, 2004 to 2026). Failure of the immune system to protect the body adequately from infection, due to the absence or insufficiency of some component process or substance. "Four children were diagnosed with hyperimmunoglobulin M syndrome (HIGM) due to CD40LG mutations, three cases had severe combined immunodeficiency (SCID), and five were diagnosed with hyper-IgE syndrome (HIES)." (PMID 39911395, 2025). "IEI diagnoses included chronic granulomatous disease, severe congenital neutropenia, CD40 ligand deficiency, severe combined immunodeficiency, Wiskott–Aldrich syndrome, hemophagocytic lymphohistiocytosis and other IEI." (PMID 39923938, 2025). "They use this approach to improve efficiency of HDR-based editing therapy for X-linked hyper IgM syndrome, an immune disorder caused by mutations in the CD40LG gene." (PMID 40012884, 2024). "X-linked hyper IgM syndrome (XHIM) is a primary immune disorder caused by inactivating mutations in the CD40LG gene, which encodes CD40 ligand (CD40L)." (PMID 40012884, 2024). "A pathogenic hemizygous in frame deletion NM_000074.3:c.436_438del (p.Tyr146del) was found in the CD40LG gene related to Immunodeficiency, X-linked, with hyper-IgM (OMIM ﻿#308230)." (PMID 37592284, 2023). "Spontaneous somatic mutations resulting in revertant mosaicism have also been described as a cause for atypical phenotypes in patients with immunodeficiency; however, we are unaware of any such case described for CD40LG deficiency." (PMID 35572607, 2022). "A literature review showed that CD40 ligand deficiency was the most common type of immune deficiency in T. marneffei infection." (PMID 36159645, 2022). "XHIGM with CD40LG mutations has been classified as combined T and B immunodeficiency, and the overall prognosis of these patients is poor, with an overall survival rate of 20–28.2%." (PMID 36419145, 2022). "Mucosal candidiasis is common in combined immunodeficiencies e.g. CD40 ligand (CD40L) deficiency, NEMO (IKBG) deficiency, IKBA gain-of-function (GOF) mutation and DOCK8 deficiency, in addition to a broad range of viral, bacterial, and IFI." (PMID 28702025, 2017). "Interestingly, the reduced incidence of Tfh cells in patients with immune deficiencies caused by mutations in CD40 ligand has raised questions about a potential role of CD40 in both the generation and maintenance of Tfh cells." (PMID 36254574, 2022). "As expected, hyper-IgM immunodeficiency was found to likely affect naïve B cells through CD40 (receptor; PrEDiCT = 2.9, FDR = 0.06), and CD4αβ T cells through CD40LG (ligand; PrEDiCT = 3.7, FDR <0.001)." (PMID 38197427, 2024). "In a systemic background of immunodeficiency (minimized by cART), B-cells receive an uncontrolled chronic activation through persistent antigenic stimulation, HIV CD40 ligand (CD40L), and HIV-encoded proteins, such as gp120, p17, and TAT." (PMID 37370801, 2023). "CD40LG mutation can cause X-linked hyper-immunoglobulin M (XHIGM), which has been classified as combined T and B immunodeficiency." (PMID 36978020, 2023). "Four children had confirmed hyperimmunoglobulin M syndrome (HIGM) with CD40LG variation, one case had severe combined immunodeficiency (SCID), and one case had hyper-IgE syndrome (HIES)." (PMID 33743629, 2021). "For example, the bone-marrow disease hyper-IgM immunodeficiency could arise from mutations in CD40 gene, affecting B cells, or mutations in CD40 ligand (CD40LG), affecting CD4 T cells." (PMID 38197427, 2024). "IgM MBCs, instead, have been also detected in individuals with severe immunodeficiencies, lacking T cells or the costimulatory molecule CD40 Ligand (CD40L)." (PMID 37304298, 2023). "X-linked hyper-IgM syndrome (XHIGM) is a combined immunodeficiency caused by mutations in CD40LG, which results in an inability to signal B cells to undergo isotype switching; thus, B cells produce only IgM and lead to elevated IgM levels and absent IgG, IgA, and IgE." (PMID 32541472, 2020).
Sepsis (162 papers, 2010 to 2026). Sepsis is defined as life-threatening organ dysfunction caused by a dysregulated host response to infection. "Clinical evidence has shown that the level of CD40 ligand (CD40L) in serum is higher in patients with sepsis and is associated with decreased survival rate." (PMID 36303116, 2022). "The reduction of CD40LG may be associated with immunosuppression in late-stage sepsis patients." (PMID 40129981, 2025). "Through docking analysis, we further validated the interaction between flavonoids and CD40LG, providing strong evidence for personalized sepsis treatment." (PMID 40129981, 2025). "In sepsis, splenic-derived protective platelet populations express high levels of CD40 ligand and release inflammatory mediators to engage in immune defense." (PMID 40909263, 2025). "Through biological experiments, we have confirmed that flavonoids can benefit sepsis patients by affecting CD40LG." (PMID 40129981, 2025). "At both gene and protein levels, CD40LG significantly decreased in sepsis patients without Xuebijing treatment compared to the healthy group, while CD40LG was partially rescued in sepsis patients with Xuebijing treatment." (PMID 40129981, 2025). "In summary, our research has identified twelve genes, including CD3E, CD40LG, LILRA5, and FCER2, as potential diagnostic markers for sepsis." (PMID 40129981, 2025). "The CD40LG may serve as a novel biomarker for the diagnosis of sepsis and as an indicator for evaluating treatment efficacy and provides a new research direction for further studying the mechanisms of immunosuppression in sepsis." (PMID 40129981, 2025). "Nevertheless, the important role of CD40LG in sepsis cannot be denied." (PMID 40129981, 2025). "Through biological experiments, we concluded that Xuebijing treatment might improve the prognosis of sepsis patients by affecting CD40LG, providing a new research direction for further studying the mechanisms of immunosuppression in sepsis." (PMID 40129981, 2025). "In sepsis, monocytes were negatively correlated with CD247, CD2, and CD40LG, while positively correlated with LCN2 and RETN." (PMID 37822934, 2023). "Drawing upon the insights gleaned from our murine sepsis-induced ARDS model and human subjects afflicted with sepsis-induced ARDS, we selected CD247, CD2, CD40LG, KLRB1, LCN2, and RETN as the foci of our subsequent investigation." (PMID 37822934, 2023). "Our findings revealed significant decreases in CD4, CD3e, IL-7R, CD5, CD247, CD2, CD40LG, ITK, and KLRB1, and significant elevations in MMP9, LCN2, and RETN in sepsis-induced ARDS compared to controls." (PMID 37822934, 2023). "Moreover, in the GSE137340 validation group, the levels of CD3E, CD40LG, FCER2, and P2RY10 expressions were markedly reduced in the sepsis group when contrasted with the control group (P < 0.05)." (PMID 40129981, 2025). "However, during sepsis, activated platelets secrete various adhesion molecules and cytokines such as P-selectin and CD40 ligand (CD40L), which interact with PSGL-1 and CD40, respectively." (PMID 38236204, 2024). "The CD40 ligand (CD40L) binds to the CD40 receptor on B cells and dendritic cells and thus influences the production of immunoglobulins and, consequently, the probability of developing sepsis." (PMID 38540968, 2024). "Moreover, we found that CD3, CD247, CD2, and CD40LG were negatively correlated with KC, whereas MMP-9, LCN2, and RETN were positively correlated with KC, suggesting that these candidate hub genes may regulate geriatric sepsis-induced ARDS by modulating the recruitment of neutrophils to the lung." (PMID 37822934, 2023).
lymphoma (160 papers, 1979 to 2026). A malignant (clonal) proliferation of B- lymphocytes or T- lymphocytes which involves the lymph nodes, bone marrow and/or extranodal sites. "Similarly, TSA elevated MHC class II protein and RNA (HLA-DR) transcription in neuroblastoma and increased MHC class I protein, RNA transcription and CD40 ligand (CD40L) expression in both lymphoma and colon cancer." (PMID 27854240, 2016). "CD19-directed CAR T-cells engineered to constitutively express CD40 ligand (CD40L, CD145) were demonstrated to have increased tumor clearance in a xenograft model of CD19+ lymphoma, increased CAR T-cell proliferation, as well as increased the secretion of pro-inflammatory Th1 cytokines." (PMID 33643299, 2020). "Specifically, for down-regulated genes: LTBR is a receptor for LTbeta in the NF-κB alternative pathway in humans and CD40LG (or CD40L) can be a ligand for NF-κB alternative pathway, both indicating canonical pathway activation in lymphoma rather than alternative pathway activation for NF-κB." (PMID 24023754, 2013).
rheumatoid arthritis (156 papers, 2003 to 2026). A chronic, systemic autoimmune disorder characterized by inflammation in the synovial membranes and articular surfaces. "CD154 (commonly referred to as CD40-ligand) is a critical T cell factor that participates in the pathogenesis of autoimmune and is over-expressed in rheumatoid arthritis (RA)." (PMID 28837666, 2017).